Y_RNA (Y RNA )
Gene: Miscellaneous RNA gene on chromosome 17 (17,460,444 to 17,460,522, forward strand). Ensembl gene ENSG00000201741.
Homologues: Orthologues: chimpanzee Y_RNA (99% identical), macaque Y_RNA (95% identical), dog Y_RNA (84% identical), tropical clawed frog Y_RNA (78% identical). Paralogues in human: Y_RNA (91% identical), RNY3 (90% identical), RNY3P1 (90% identical), Y_RNA (90% identical), Y_RNA (89% identical), Y_RNA (87% identical), Y_RNA (86% identical), RNY3P16 (85% identical), Y_RNA (85% identical), RNY3P11 (84% identical), Y_RNA (84% identical), RNY3P14 (82% identical), and 89 more.